ASS1 (argininosuccinate synthase 1)
Diseases named in the same sentence as ASS1 in open-access papers (continued):
Sharing a sentence is not in itself a finding about the gene and the disease.
fibrosis (1 paper, 2021). the formation of excess fibrous connective tissue in an organ or tissue in a reparative or reactive process. "We found the expression of OTC, CPS1, ASS1, and ASL was highly upregulated in BLM-induced fibrosis, and these enzymes were also downregulated after treatment with TL." (PMID 33995084, 2021).
hepatitis B infection (1 paper, 2021). "ASS1 expression was quantified by western blotting in tissue from 58 Korean patients with nodular liver cancer and hepatitis B infection." (PMID 33838671, 2021).
Insulin resistance (1 paper, 2019). Increased resistance towards insulin, that is, diminished effectiveness of insulin in reducing blood glucose levels. "Serine hydroxymethyltransferase 1 (SHMT1), ALDOC, SDSL, ASS1, and IDH3A are novel biomarkers for the development of insulin resistance." (PMID 30678306, 2019).
kidney cancer (1 paper, 2019). Primary or metastatic malignant neoplasm involving the kidney. "ASS1 was downregulated in kidney cancer cells, but upregulated in normal proximal tubule cells, which made cells rely on extracellular sources of arginine for survival." (PMID 31727869, 2019).
liver failure (1 paper, 2022). A liver disease characterized by the liver losing or has lost all of its function. "Many (38.5%) of our neonatal classic CTLN1 patients (P1–P5) were homozygous for a common mutation of ASS1 (c.1168G>A; p.Gly390Arg), which caused the most fulminant disease course, leading to liver failure and early neonatal death despite treatment." (PMID 35433176, 2022).
liver steatosis (1 paper, 2024). "In line with changes in liver weight, the transplant of Acod1-/- fecal microbiota in wild-type mice also decreased liver steatosis and increased hepatic mRNA levels of Nags, Cps1 and Ass1 urea cycle genes." (PMID 38302438, 2024).
medulloblastoma (1 paper, 2022). A malignant, invasive embryonal neoplasm arising from the cerebellum. "Multiple drugs are in development in other tumors that target the urea cycle through inhibition of aspartate or ASS1, and some of these agents could be applied to medulloblastoma tumors with vulnerable metabolic profiles." (PMID 35267619, 2022).
meningioma (1 paper, 2025). A generally slow growing tumor attached to the dura mater. "The results showed that several clusters of meningioma cells expressed ASS1, while nearly all meningioma cell clusters exhibited negligible expression of ASL." (PMID 41184266, 2025). "We analyzed the expression of ASS1 and ASL in 11 clusters of meningioma cells." (PMID 41184266, 2025).
neuroendocrine carcinoma (1 paper, 2021). A malignant neuroendocrine neoplasm composed of cells containing secretory granules that stain positive for NSE and chromogranin. "Similarly, patients with urinary bladder high-grade neuroendocrine carcinomas (HGNECs) have shown an absence of ASS1 expression." (PMID 34447409, 2021).
oral squamous cell carcinomas (1 paper, 2021). "According to this data and previous findings in oral squamous cell carcinomas, the high level of ASS1 seems to be a reliable independent prognostic marker of poor disease-free survival in HNSCC patients." (PMID 33230565, 2021).
osteoarthritis (1 paper, 2022). A noninflammatory degenerative joint disease occurring chiefly in older persons, characterized by degeneration of the articular cartilage, hypertrophy of bone at the margins and changes in the synovial membrane. "This analysis, and subsequent experimental confirmation, revealed five novel osteoarthritis-associated proteins (PPIB, ASS1, LHDB, TPI1, and ARPC4-TTLL3)." (PMID 35457215, 2022).
ovarian tumor (1 paper, 2022). "Aberrant methylation in the promoter of ASS1 makes ovarian tumor cells more resistant to platinum-induced cell death." (PMID 35910381, 2022). "For instance, epigenetic silencing of ASS1 confers ovarian tumor cells resistance to platinum chemotherapy." (PMID 35910381, 2022).
pancreatic adenocarcinoma (1 paper, 2021). "Analysis of murine pancreatic adenocarcinoma (PDAC) tissue, which is associated with ARG2 and ASS1 upregulation, found a dramatic reduction in arginine levels in the interstitial fluid." (PMID 33979616, 2021).
papilloma (1 paper, 2022). A benign epithelial neoplasm that projects above the surrounding epithelial surface and consists of villous or arborescent outgrowths of fibrovascular stroma. "For example, CEBPB−/− mice are completely resistant to papilloma induced by chemical carcinogens, which was in accord with our report that silencing of CEBPB can increase ASS1 expression and alleviate the malignant biological behaviors and tumor progression." (PMID 35674458, 2022).
thoracic cancer (1 paper, 2022). A primary or metastatic malignant neoplasm affecting the tissues of the thorax. "Although we have found evidence to support FLT-PET imaging in the evaluation of the arginine-ASS1-ADI pathway in thoracic cancers (especially MPM), the small sample size, high dropout, wide confidence intervals, and barely significant p values suggest that further evaluation is warranted." (PMID 36082278, 2022). "Hence, although FLT-PET imaging lacks robustness for early time point imaging, this study provides evidence for its use in the evaluation of the arginine-ASS1-ADI pathway in thoracic cancers, especially in MPM." (PMID 36082278, 2022).
viral myocarditis (1 paper, 2025). Myocarditis that is caused by an infection with a viral agent. "By activating ASS1, macrophages polarization is affected and viral myocarditis promoted." (PMID 40608831, 2025).
cancer (213 papers, 2010 to 2026). A tumor composed of atypical neoplastic, often pleomorphic cells that invade other tissues. "The key mechanism proposed in ASS1 downregulation is the hypermethylation of the ASS1 promoter, resulting in loss of ASS1 expression in cancer cells." (PMID 41300990, 2025). "The ASS1-deficient cancer cells, with their high demand for L-arg and inability to synthesize it, enter a starvation state and become cytostatic." (PMID 41295280, 2025). "The effects of ADI-PEG20 on cell-cycle regulation, apoptosis, and BCL-XL–mediated survival pathways in ASS1-deficient cancer cells were determined." (PMID 39898973, 2025). "Some trials defined ASS1 loss as less than 5% positive cancer cells in immunohistochemical staining, while others used a threshold of less than 50% positive cancer cells, or employed only semiquantitative evaluation systems." (PMID 41300990, 2025). "Understanding the mechanism of resistance and finding a way to overcome it remain a challenge, but it is necessary for ADI-PEG20 therapy to improve long-term outcomes for patients with ASS1- deficient cancer." (PMID 39758821, 2025). "Loss of ASS1 contributes to DNA damage and promotes cell cycle progression, likely contributing to cancer mutagenesis and, hence, adaptability potential." (PMID 38858597, 2024). "Similar to our results in cancer cells, ASS1-deficient skin fibroblasts had significantly lower survival following Dox treatment than control fibroblasts." (PMID 38858597, 2024). "Suppressed ASS1 levels in cancer results in tumor auxotrophy (a tumor dependent on extracellular arginine) and is associated with poor outcomes in many cancers." (PMID 39585048, 2024). "This is because HIF-1 upregulation is associated with increased arginine consumption (due to ASS1 inhibition) in cancer cells." (PMID 37445845, 2023). "Most cancer cells lose the capacity of intracellular arginine synthesis because of the loss of a key enzyme that produces arginine, argininosuccinate synthetase 1 (ASS1)." (PMID 37214463, 2023). "In other cancers, high ASS1 is associated with poor prognosis and increased purine synthesis, potentially sensitizing cells to mizoribine." (PMID 36669126, 2023). "Loss of ASS1 promotes cancer proliferation by diverting its substrate, aspartate, toward pyrimidine synthesis (carbamoyl-phosphate synthetase 2 (CPS2), aspartate transcarbamylase (ATC), and dihydroorotase." (PMID 38136342, 2023). "In invasive bladder cancers, it has been demonstrated that ASS-1 loss promotes cancer cell survival through GCN2 expression, and that administration of ADI-PEG-20 causes apoptosis through GCN2/ATF4 mediated CHOP activation." (PMID 39516654, 2023). "Arginine is a semi-essential amino acid which becomes wholly essential in many cancers commonly due to the functional loss of Argininosuccinate Synthetase 1 (ASS1)." (PMID 36903394, 2023). "Low ASS1 expression is associated with poor prognosis and resistance to conventional chemotherapy in various types of cancer." (PMID 37445845, 2023). "Owing to a deficiency of ASS1, cancer cells become addicted to external arginine and resistant to GEM." (PMID 35646101, 2022). "Although increasing evidence suggests that ASS1 deficiency drives metabolic adaptations to support tumor cell growth, in some cases, ASS1 contributes to cancer cell survival by modulating autophagy and signal transduction." (PMID 35864952, 2022). "Since ASS1-deficient tumor cells rely on extracellular arginine for survival, arginine deprivation is a therapeutic strategy for these cancers." (PMID 36686230, 2022). "Here, the median PFS and OS were 4.2 (95% confidence interval: 2.9–4.8) and 7.2 (95% confidence interval: 5.1–18.4) months, respectively, and consistent with the poor prognosis of ASS1-deficient cancers." (PMID 36082278, 2022).
cancer (continued). "Preclinical data demonstrated that depletion of arginine by PEGylated arginine deiminase (ADI‐PEG 20) enhanced liposomal doxorubicin (PLD) cytotoxicity in cancer cells with argininosuccinate synthase 1 (ASS1) deficiency." (PMID 34841717, 2022). "Another example of cancer metabolism is the abandonment of arginine synthesis due to ASS1 deficiency." (PMID 36319669, 2022). "ASS1 deficiency has been associated with accelerated tumourigenesis and more aggressive cancers, conferring worse survival outcomes." (PMID 35466524, 2022). "Based on preclinical data demonstrating that ADI‐PEG 20 combined with chemotherapy synthetically killed cancer cells harboring ASS1 deficiency, investigators have explored several combination therapeutic regimens in a number of clinical studies." (PMID 34841717, 2022). "One of these promising targets is the arginine dependence in a subset of SCLCs, which is related to the ASS1-deficiency of the cancer cells and can be therapeutically exploited." (PMID 34958428, 2021). "For example, loss or reduced expression of ASS1 is manifest in several cancer types and ASS1-deficient cancer cells are totally reliant on extracellular arginine." (PMID 34068137, 2021). "ASS1-deficient cancer cells show synthetic lethality and an inhibited Warburg phenotype under arginine depletion." (PMID 34041023, 2021). "Development of anti‐ADI‐PEG20 antibodies alongside an elevation in arginine levels was considered a possible reason for the treatment failure of ADI‐PEG20 in patients with ASS1‐deficient cancer." (PMID 33787078, 2021). "Another drug that selectively targets ASS1-deficient cancer cells is ADI-PEG20, which is an arginine deiminase (ADI) PEGylated with 20,000 molecular weight polyethylene glycol (PEG)." (PMID 34958428, 2021). "ADI‐PEG20 is pegylated arginine deiminase, which can induce the depletion of arginine via rapid conversion of arginine into citrulline, which inhibits the proliferation of various ASS1‐deficient cancer cells in vitro and in vivo." (PMID 33787078, 2021). "As ASS1 is a key enzyme for arginine biosynthesis, arginine depletion results in specific cell death of ASS1-deficient cancer cells." (PMID 33859183, 2021). "This evidence suggests that silencing of the ASS1 enzyme is associated with poor prognosis in patients with malignant tumors." (PMID 33598460, 2021). "ASS1 deficiency has been observed in various cancers, including MFS, due to epigenetic silencing of its promoter." (PMID 34294128, 2021). "The first limitation on the effectiveness of this monotherapy is the requirement of arginosuccinate synthetase 1 (ASS1) deficiency in the targeted cancers." (PMID 33478072, 2021). "Numerous cancers have been shown to be ASS1‐deficient; hence, cancer cells are dependent on exogenous arginine." (PMID 33787078, 2021). "For some cancers with deficiency of arginine metabolic enzymes such as argininosuccinate synthase 1 (ASS1), arginine deprivation has been considered as a promising strategy." (PMID 35006438, 2021). "The suppressed expression of ASS1, mainly due to promoter methylation, is making it the most prevalent metabolic deficiency of cancer and rendering cancer cells “addicted” to external arginine." (PMID 34298755, 2021). "ARG2 was expressed mainly by cancer-associated fibroblasts (CAFs) (58/98 cases; 59.2%), while ASS1 by cancer cells (75/98 cases; 76.5%)." (PMID 34344457, 2021). "Although the loss of ASS1 expression is reported in a variety of cancers, we show reduced expression of both ASS1 and ASL in ccRCC tumors." (PMID 34861885, 2021). "Silencing of ASS1 in these cancers is associated with tumor progression, resulting from increased pyrimidine synthesis, caused by a higher availability of aspartate." (PMID 34599156, 2021). "This was also verified in linear regression analysis, where an inverse association between the % of ASS1 expressing cancer cells and MVD was noted (p = 0.03, r = 0.22)." (PMID 34344457, 2021).
cancer (continued). "ASS1 expression by cancer cells was associated with a high density of iNOS-expressing tumor-infiltrating lymphocytes (iNOS+TILs)." (PMID 34344457, 2021). "Arginine addiction induced by argininosuccinate synthase (ASSN1) deficiency has been exploited to treat ASS1-deficient cancers." (PMID 33859183, 2021). "We used an established organotypic model 23, 36 where ASS1-low MiaPaca2 cells were co-cultured with PDAC cancer-associated fibroblasts (CAFs)." (PMID 31903153, 2020). "Since the gene encoding argininosuccinate synthetase 1, ASS1, undergoes epigenetic silencing in multiple types of cancer, we tested its protein expression, which was barely detectable in CAL-120 cells." (PMID 30613774, 2019). "An immunohistochemistry (IHC) analysis confirmed the ASS1 deficiency of cancer cells and showed ASS1-positive stromal cells and vascular endothelium in tumor tissue." (PMID 30613774, 2019). "Somatic silencing of the ASS1 enzyme in the urea cycle was exhibited in many cancers and tumor tissues, and it was reported that loss of the ASS1 is associated with poor outcomes." (PMID 30483387, 2018). "ASS1 expression can also be downregulated in some cancers in association with the methylation of its promoter." (PMID 30082427, 2018). "In this biomarker-selected group of patients with ASS1-deficient cancers, clinical activity was observed in patients with poor-prognosis tumors." (PMID 28388291, 2017). "Most commonly, single-agent treatment of ASS1-deficient cancer cells with ADI-PEG20 induces apoptosis." (PMID 27735949, 2016). "The treatment of ASS1-deficient cancers is complicated by the ability of tumors to re-express ASS1, thus there is a need to identify additional targets for synthetic lethality based on the ASS1 deficiency." (PMID 27735949, 2016). "Although the reason for reduced ASS1 expression in certain types of cancer that generally have a poor prognosis remains to be elucidated, reduced ASS1 expression has been noted to be associated with resistance to chemotherapy." (PMID 27683125, 2016). "Critically reduced ASS1 enzyme level can result in the inability of cancer cells to utilize citrulline for arginine synthesis and ASS1 deficiency was thus adopted as a marker of arginine auxotrophy and sensitivity to arginine deprivation." (PMID 27689335, 2016). "Because STAT3 is associated with the metastatic behavior of cancer cells, wehypothesized that ASS1 suppression inhibits STAT3 expression in gastric cancercells." (PMID 25928182, 2015). "DNA methylation of the ASS1 promoter leading to its downregulation was associated with poor prognosis and chemoresistance in various cancers." (PMID 24416132, 2014). "The significance for ASS1 loss in cancer is currently unclear; however, several groups have revealed that reduced expression of ASS1 is a predictive biomarker for the development of metastasis and is associated with a worse clinical outcome." (PMID 25164070, 2014). "Therefore, therapeutic strategies to deplete arginine are considered promising and have been shown to be particularly effective in argininosuccinate synthetase 1 (ASS1)‐deficient cancers, as ASS1 is the rate‐limiting enzyme of arginine synthesis." (PMID 40552664, 2025). "Thus, ASS1 regulation of pyrimidine levels has diagnostic and therapeutic implications for cancer patients." (PMID 38858597, 2024). "However, ASS1, the rate-limiting enzyme in urea cycle, is usually downregulated in cancer and its downregulation has been reported to be associated with advanced tumor stage." (PMID 38218942, 2024). "Moreover, loss of urea cycle enzymes in HCC renders cancer cells auxotrophic for arginine, and argininosuccinate synthase 1 (ASS1) downregulation enables cancer cells to accumulate aspartate for pyrimidine synthesis necessary for cell proliferation." (PMID 39872506, 2024).